MTOR (mechanistic target of rapamycin kinase)
Diseases named in the same sentence as MTOR in open-access papers (continued):
Sharing a sentence is not in itself a finding about the gene and the disease.
breast cancer (continued). "These highly cited articles not only demonstrate the important role of the mTOR signaling pathway in the development of breast cancer, but also provided a theoretical rationale and clinical evidence for mTOR inhibitors as a potential therapeutic strategy." (PMID 37637052, 2023). "Everolimus is another inhibitor of mTOR, approved worldwide from clinical trials to clinical practices for the treatment of breast cancer in combination with exemestane (an aromatase inhibitor)." (PMID 37190133, 2023). "For example, the mTOR inhibitor everolimus has shown anticancer activity when combined with exemestane in the treatment of advanced breast cancer." (PMID 37637052, 2023). "The keyword analysis revealed that the application of mTOR inhibitors in the treatment of breast cancer was initially the focus of research in this field." (PMID 37637052, 2023). "The researchers used mathematical modeling to investigate the signaling networks that govern mTOR hyperactivation in breast cancer cells." (PMID 38046946, 2023). "Magnoflorine promotes the anticancer effects of doxorubicin by inducing cellular apoptosis and autophagy in breast cancer cells by regulating the p62, mTOR, and p38 signaling pathways." (PMID 37249285, 2023). "For instance, HIF-1α has been associated with growth, metastasis and treatment resistance in breast cancer by activating the PI3K/Akt/mTOR pathway." (PMID 36674861, 2023). "This regulates the stability of SLC1A5 protein, thereby reducing the uptake of glutamine by cells, inhibiting the mechanistic target of rapamycin (mTOR)-signaling pathway and reducing the growth rate of breast cancer cells." (PMID 37190313, 2023). "Data on 739 patients with breast cancer, among which 125 patients had adjacent-normal tissue, with tumor expression for mTOR, phosphorylated (p)-mTOR, p-AKT, and p-P70S6K were analyzed." (PMID 36895729, 2023). "Anti-metastasis via down-regulation of ROS (reactive oxygen species) and PI3/Akt/mTOR in lung cancer cells, and CuB via downregulation of the pFAK pathway in breast cancer." (PMID 37887406, 2023). "Collectively, our data demonstrated that MYC drives resistance to clinically approved mTOR-targeted therapies in mouse models of murine and human breast cancer." (PMID 37642941, 2023). "have found that a combination of mTOR inhibitor everolimus and metformin had a synergistic effect on inhibiting breast cancer cell growth." (PMID 37251941, 2023). "Berberine inhibited autophagy by participating in the PTEN/Akt/mTOR pathway by reversing doxorubicin resistance in breast cancer." (PMID 36619229, 2023). "In a similar phase III study with HR+ and HER2− breast cancer patients with disease which reverted during or after an mTOR inhibitor, buparlisib increased PFS from 4 to 6.8 months." (PMID 37190133, 2023). "The researchers also looked at the significance of mTOR signaling in breast cancer cell resistance to targeted therapy." (PMID 38046946, 2023). "Proteins activated as a result of HER2 signalling, including GSK3β and mTOR, are currently being evaluated in breast cancer with mixed outcomes." (PMID 36670508, 2023). "Several PI3K/AKT/mTOR inhibitors have been evaluated for the treatment of refractory ER + breast cancer." (PMID 36792625, 2023). "The FA-BSANPs/BA nanoparticles were found to elevate ROS levels, inactivate AKT/mTOR signaling, and induce cytotoxic autophagy and apoptosis in breast cancer." (PMID 36678588, 2023). "A dipeptidyl peptidase (DPP)-4 inhibitor accelerated breast cancer metastasis by inducing EMT through CXCL12/CXCR4/mTOR axis, while metformin countered the harmful effect of DPP-4 inhibitor on breast cancer metastasis." (PMID 37497001, 2023).
breast cancer (continued). "Oleocanthal has exhibited robust anti-proliferative effects in multiple breast cancer cell lines, accompanied by the downregulation of phosphorylated mTOR in a metastatic breast cancer cell line, specifically MDA-MB-231." (PMID 38136231, 2023). "The frequent activation of the PI3K/AKT/mTOR pathway observed in ER+ breast cancer and its implication in the development of acquired endocrine resistance has made it a key target for pharmacologic intervention in this patient population." (PMID 36901954, 2023). "In vivo pharmacodynamic studies showed that LXI-15029 had a selective antitumor activity in human renal carcinoma, gastric cancer, breast cancer, and lung cancer with abnormal regulation in the mTOR signaling pathway in nude mouse xenograft models." (PMID 38057772, 2023). "About 60% of all breast cancer tumors have the Akt/mTOR pathway activated due to genetic alterations, which contributes to therapy resistance." (PMID 37190229, 2023). "Canagliflozin and dapagliflozin were found to activate AMPK, which led to inhibition of mTOR in breast cancer." (PMID 37436535, 2023). "In recent years, the focus of research has shifted to the mechanism of action of the mTOR signaling pathway in the occurrence and development of breast cancer." (PMID 37637052, 2023). "ProE and ProE-NLC have shown potential anti-breast cancer activity through multiple interrelated mechanisms including, the elevation of antioxidant levels, suppression of angiogenesis, inflammatory and mTOR pathways, and induction of the apoptotic pathway." (PMID 37735586, 2023). "The PI3K/Akt/mTOR signaling pathway is one of the most common dysregulated signaling pathways in breast cancer, leading to increased cell proliferation and survival." (PMID 37175104, 2023). "Similar results were obtained for the cells of other tumor types, including HeLa (cervical cancer) and MDA-MB-231 (breast cancer) cells, suggesting that pharmacological VC can inhibit the mTOR pathway in a variety of cancer cells." (PMID 36787291, 2023). "Using the transplantable KEP model, we here performed multiomic analyses of ILC tumors obtained during long-term mTORi treatment to study in vivo mechanisms of acquired resistance to mTOR inhibition in breast cancer." (PMID 37642941, 2023). "Further, TMEM97 increases the resistance of breast cancer cells to tamoxifen through elaborating the mTOR/S6K1 signaling." (PMID 38067394, 2023). "For example, the combination of CDK4/6 inhibitors with PI3K/AKT/mTOR pathway inhibitors such as alpelisib in breast cancer cell lines and patient-derived models has demonstrated that alpelisib can overcome resistance mediated by PI3K pathway activation." (PMID 37511548, 2023). "mTOR is crucially involved in breast cancer pathogenesis, but its exact mechanism of action remains controversial and warrants further investigation." (PMID 37637052, 2023). "The bibliometric analysis of mTOR and breast cancer promotes a better understanding of the frontier knowledge and research hotspots in this field." (PMID 37637052, 2023). "LNT inhibited macrophage M2 polarization and subsequently blocked the AKT/mTOR and inflammatory signaling axes in breast cancer cells, thereby promoting autophagic tumor cell death." (PMID 37249285, 2023). "Breast cancer patients usually exhibit a high concentration of thrombin, which promotes the expression of cyclin D1 by activating the mTOR and Wnt/β-catenin signaling pathways." (PMID 36677797, 2023). "As Luteolin reduced the levels of activated PI3K/Akt/mTOR signaling cascade, the combination of Luteolin and PI3K, Akt, or mTOR inhibitors resulted in the synergistic increase in apoptosis in Tamoxifen-resistant ER-positive breast cancer cells." (PMID 36992138, 2023). "When predicting the sensitivity of breast cancer cell lines to Torin2, a polyselective mammalian target of rapamycin (mTOR) inhibitor, we found that 526 out of 673 rankable pairs were ranked correctly by a random forest model (AUC estimate = 0.78)." (PMID 37602225, 2023).
breast cancer (continued). "EVL, an oral mTOR inhibitor, is widely used as an immunomodulatory agent in the treatment of neuroendocrine tumors, renal cancer, breast cancer, and other diseases." (PMID 37140396, 2023). "According to these results and the previous ones obtained in colon and breast cancers, we can suggest that the depletion of mTOR is due to the synergistic interaction of the drug combination." (PMID 37223676, 2023). "Cancer therapy targeting the PI3K/mTOR signaling pathway is expected to have an antitumor effect against canine mammary cancer and melanoma." (PMID 36816969, 2023). "Magnoflorine has been shown to activate p38 and inhibit AKT/mTOR signaling pathways to induce autophagy, which further exacerbated doxorubicin-induced apoptosis, thereby increasing the sensitivity of breast cancer cells to doxorubicin." (PMID 36678588, 2023). "In dogs, mTOR phosphorylation has been detected by immunohistochemistry in various tumors, such as mammary tumors, squamous cell carcinoma, trichoblastoma, myxosarcoma, hemangiosarcoma, and prostate cancer." (PMID 36816969, 2023). "One of the most commonly altered pathways driving breast cancer cell progression is the PI3K/AKT/mTOR signaling cascade, whereas also the N-terminal c-Jun kinase (JNK) and extracellular-signal-regulated kinase (ERK) in the MAPK pathway have been implicated." (PMID 37371498, 2023). "This suggests that VeM-ECs with enhanced PI3K/AKT/mTOR signaling, similar to their breast cancer counterparts, show high proliferative potential, decreased genomic stability, and increased invasiveness." (PMID 37109059, 2023). "This is a key intracellular signaling system that drives cellular growth and survival, and emerging evidence indicates that hyperactivation of the PI3K/AKT/mTOR pathway is a key mechanism of endocrine resistance in HR+ breast cancer." (PMID 36263515, 2023). "Everolimus was the first mTOR inhibitor approved for ER + HER2- patients with advanced breast cancer who relapsed to hormone therapy." (PMID 36792625, 2023). "The frequent activation of the PI3K/AKT/mTOR pathway and its crucial role in estrogen receptor-positive (ER+) breast cancer tumorigenesis and drug resistance has made it a highly attractive therapeutic target in this breast cancer subtype." (PMID 36901954, 2023). "Similar to CDK4/6 inhibitors, small molecule inhibitors of the PI3K/AKT/mTOR pathway are also FDA approved for use in endocrine resistant ER+/HER2-breast cancer in combination with ET." (PMID 37035239, 2023). "Previous studies have demonstrated that GARS1 promotes the cell cycle, migration, and invasion of breast cancer cells by regulating the AKT/mTOR signaling pathway." (PMID 37404826, 2023). "Melittin, the main peptide component of Apis mellifera venom, inhibits EGF-induced cell movement and invasion by inhibiting the PI3K/Akt/mTOR signalling pathway in breast cancer cells." (PMID 37033662, 2023). "Alpelisib (targeting the PI3K catalyst subunit α or PI3KCA) and everolimus (targeting mTOR) are already approved by the FDA for the treatment of HR-positive, HER2-negative breast cancers (with a PIK3CA mutation for alpelisib)." (PMID 37759706, 2023). "In support of this, another study found that the PI3K/Akt/mTOR pathway played a prominent role in maintaining breast cancer stem-like cells." (PMID 38017510, 2023). "In summary, PI3K pathway activation was shown to promote acquired resistance to long-term endocrine deprivation in preclinical models of ER+ breast cancer cell lines, and proteomic profiling revealed increased phosphorylation of mTOR and Akt." (PMID 38003387, 2023). "In accordance with cell-based experiments, in vivo experiments have confirmed that fisetin (20, 40, and 80 μM) is able to counteract tumor growth in a 4T1 orthotopic mammary tumor model by reducing the activation of PI3K/Akt/mTOR signaling pathway." (PMID 37891924, 2023).
breast cancer (continued). "Lentinus edodes (LNT) inhibited macrophage M2 polarization, and subsequently blocked the AKT/mTOR and inflammatory signaling axis in breast cancer cells, thereby promoting autophagic tumor cell death." (PMID 37249285, 2023). "Several medicines targeting PI3K/AKT/mTOR signaling in breast cancer have reached the pre-clinical development stage." (PMID 37287817, 2023). "We found that the cytoplasmic level of MTA1 was significantly negatively correlated with the response of breast cancer patients to mTOR inhibitors." (PMID 37442756, 2023). "Deglycosylated EpCAM enhances autophagy of cancer cells via PI3K/Akt/mTOR pathway in breast cancer cells." (PMID 37834237, 2023). "The phosphoinositide 3 kinase (PI3K)/AKT/mammalian target of rapamycin (mTOR) pathway plays a critical role in cell growth, tumor proliferation, and therapy resistance in breast cancer." (PMID 37237509, 2023). "Cell death and autophagy were triggered in breast cancer cells by inhibiting the Akt/mammalian target of the rapamycin (mTOR) pathway." (PMID 37110140, 2023). "The positive clinical outcomes of adding inhibitors of the PI3K/Akt/mTOR pathway demonstrate that these agents including everolimus and alpelisib can restore hormone sensitivity in breast cancer." (PMID 38003387, 2023). "TAMs secrete chemokines and activate the PI3K–Akt–mTOR signaling pathways, increasing endocrine resistance in breast cancer." (PMID 37627528, 2023). "They discovered that oncogenic protein kinase C (PKC) activation plays a crucial role in the hyperactivation of mTOR signaling in breast cancer cells." (PMID 38046946, 2023). "Sirolimus (mTOR inhibitor), an allosteric mTORC1 inhibitor, suppresses the growth of breast cancer cells." (PMID 36619229, 2023). "The activation of mTOR was observed in both sphere-forming cells and adherent cells of canine mammary cancer, and 4E-BP, which is an mTOR downstream signal, was activated in sphere-forming cells." (PMID 36816969, 2023). "Our recent study showed that metformin mitigates DPP-4 suppression-induced breast cancer growth and metastasis by mTOR regulation." (PMID 37760498, 2023). "A breast cancer study has shown that CKAP2L activates the AKT/mTOR signaling pathway and thus promotes breast cancer development." (PMID 37225919, 2023). "The Western blot results indicated that LHX2 activated the PI3K/AKT/mTOR pathway and apoptosis pathway in breast cancer, and it inhibited the apoptosis of BRCA." (PMID 37345110, 2023). "On the other hand, as a result of decreasing the levels of HER2 in breast cancer cells, metformin can inhibit breast carcinoma cell growth, and inhibition of p70S6K1, an effector of the mTOR pathway, can mediate this effect." (PMID 36849958, 2023). "The mTOR inhibitor, everolimus, is an important clinical management component of metastatic ER+ breast cancer (BC)." (PMID 37772709, 2023). "An mTOR-inhibitor, zortress (42-O-(2-hydroxyethyl)rapamycin) has been authorized for advanced or metastatic aromatase antagonist-resistant ER + breast carcinoma." (PMID 37415164, 2023). "Taken above, these data indicate that deglycosylated EpCAM-induced autophagy participated in the proliferation an apoptosis viaI3K/Akt/mTOR signaling in breast cancer cells." (PMID 34983878, 2022). "Breast cancer models of hyperactive PI3K/Akt/mTOR pathway have shown resistance to targeted therapy." (PMID 35800378, 2022). "Taken together, these results demonstrate, for the first time, that factors released from skeletal muscle suppress anabolism in breast cancer via action on the canonical mTOR pathway." (PMID 36388131, 2022). "Lupiwighteone, a Cadophora gregata-derived compound, triggers apoptosis in breast cancer cells by inactivating PI3K/AKT/mTOR." (PMID 36139919, 2022). "A previous study reported that endocrine resistance was significantly repressed with mTOR inhibitor treatment in breast cancer." (PMID 35464065, 2022).
breast cancer (continued). "We also found that deglycosylated EpCAM promoted apoptosis and inhibited proliferation through activating autophagy by suppressing Akt/mTOR signaling pathway in breast cancer cells." (PMID 34983878, 2022). "Previous studies have also reported that Se/FO supplements target EGFR/TβR/AXL/PI3K/Akt/mTOR signaling and therefore increase the apoptotic efficacy of anti-cancer agents in breast-cancer-bearing mice and NSCLC cells." (PMID 36547898, 2022). "The underlying mechanism of CUR-increased chemosensitivity was correlated with downregulation of CCAT1 expression and inactivation of PI3K/Akt/mTOR pathway in treated breast cancer cells." (PMID 35216255, 2022). "To confirm that SCA-mediated autophagy was driven by mTOR signaling, we used the mTOR agonist MHY1485 in combination with SCA or alone to observe its effects on autophagy in breast cancer cells." (PMID 36408240, 2022). "The clinical development of therapeutics that target the PI3K/Akt/mTOR pathway in ER+ breast cancer has met with significant challenges." (PMID 36046843, 2022). "To understand the mechanism of deglycosylated EpCAM-mediated autophagy in breast cancer cells, we analyzed the Akt-mTOR signaling pathway." (PMID 34983878, 2022). "CC-chemokine ligand 2 (CCL2) secreted by TAMs was revealed to activate the PI3K/AKT/mTOR pathway in breast cancer cells, thus induced resistance to tamoxifen treatment in breast cancer." (PMID 36151545, 2022). "Flavonoids target mTOR signaling in breast cancer, and when this signaling pathway is regulated or deregulated, various signaling pathways provide potential therapeutic means." (PMID 35795855, 2022). "Chrysophanol inhibits cell proliferation by the inhibition of the NF-κB and EGFR/mTOR pathways in colon and breast cancers." (PMID 36676666, 2022). "Currently, there are a range of drugs in clinical trials that target various parts of the PI3K/AKT/mTOR pathway, however, only few are approved for the treatment of breast cancer." (PMID 36045910, 2022). "The regulation and deregulation of the mTOR signaling pathway by flavonoids provide a new insight for its mechanism of action in breast cancer treatment." (PMID 35795855, 2022). "In summary, we found that SCA promoted breast cancer cell apoptosis by inhibiting the PI3K–Akt–mTOR pathway and inducing autophagy." (PMID 36408240, 2022). "Western blot analysis indicated that rapamycin treatment reversed the increase in the accumulation of activated (i.e., phosphorylated) AKT/mTOR proteins observed in ATRAP-overexpressing breast cancer cell lines." (PMID 35414770, 2022). "The role of various flavonoids as phytochemicals in targeting mTOR signaling pathways in breast cancer is highlighted in this review." (PMID 35795855, 2022). "Our study demonstrated that the effect of Akt-mTOR signaling on the regulation of autophagy in breast cancer cells." (PMID 34983878, 2022). "We further applied the biomarker to predict mTOR inhibitor response in an independent cohort of ER+/HER2- breast cancer patients from the METABRIC study." (PMID 36304922, 2022). "Among these mechanisms, targeting the mTOR signaling pathway in breast cancer was identified as a potent target that overcomes the issue of chemoresistance." (PMID 35795855, 2022). "mTOR signaling in breast cancer is active and driven by multiple genetic aberrations within the PAM pathway." (PMID 35884439, 2022). "Acacetin in breast cancer resulted in autophagy and apoptosis induction trough suppression of the Akt/mTOR signaling pathway." (PMID 35795855, 2022). "Cepharanthine can induce autophagy by inhibiting Akt/mTOR signaling in human breast cancer MCF-7 and MDA-MB-231 cells, and stimulating AMPK-mTOR-dependent autophagy to induce apoptosis-tolerant cell death." (PMID 35684449, 2022). "In breast cancer cells, statin has also been found to enhance the anticancer effects of chemopreventive agents by inhibiting the mTOR pathway." (PMID 36431025, 2022).